NF1 (neurofibromin 1)
Diseases named in the same sentence as NF1 in open-access papers (continued):
Sharing a sentence is not in itself a finding about the gene and the disease.
tumor (continued). "Comparison of median tumor volumes at baseline and at follow-up in age-dependent subgroups of NF1 patients with type-1 deletions vs NF1 patients without large deletions of the NF1 gene (control)." (PMID 33951044, 2021). "In elderly HGSOC, mutations in the genes that are involved in the Ras and or PIK3CA signaling pathways were detected in nine samples (15%), including the genes KRAS and BRAF (each one in 1 tumor); PIK3CB and MTOR (each one in 2 tumors); and NF1 (in three different samples)." (PMID 34944094, 2021). "In conclusion, NF1 caused by NF1 whole gene deletions leads to a more severe phenotype with higher tumor burden and higher tumor growth rates when compared to NF1 patients without large deletions of the NF1 gene." (PMID 33951044, 2021). "TAMs are enriched in the mesenchymal GBM and are associated with NF1 mutation, whereas CD8+ and CD4+ tumor-infiltrating lymphocytes (TILs) are absent from the classical and IDH-mutant proneural tumor." (PMID 34359588, 2021). "Sequencing of the lymph node sample revealed an NF1 intragenic inversion that was not present in the pre-treatment tumor." (PMID 34795269, 2021). "Mice where the GVC-administration reduced mean tumour weight (LV-miniMg-Full-HSV and LV-miniMg-∆MEF3/NF1-HSV) also showed a net reduction in mean body weight during the treatment period, while control mice with LV-∆miniMg-HSV demonstrated a mean gain in body weight." (PMID 32973362, 2021). "Fourth, the mean age for patients with NF1 who did not develop additional neoplasms was similar to the mean age for those who did develop neoplasms." (PMID 33734413, 2021). "With the exception of clonal Pdgfra and Nav3 insertions in one tumor, transposon insertions in MAPK/PI3K pathway and neurodevelopmental genes (including Nf1, Pten, Pik3r1, Ptprj, Sox6, Sox5, and Tcf4) were subclonal in these tumors, implying these were late evolutionary events." (PMID 32727536, 2020). "By contrast, only 17 (61%) of 28 age-matched NF1 patients without microdeletions had internal tumours." (PMID 32533297, 2020). "Finally, multi-regional sampling was also performed on a subset of nine fresh frozen NF1-related MPNST specimens to assess intra-tumor variation (i.e., tumor heterogeneity) by performing 500× exome sequencing, RNA-seq, and epigenetic profiling." (PMID 32252413, 2020). "The total internal tumour load was significantly higher in NF1 microdeletion patients than in NF1 patients without microdeletions." (PMID 32533297, 2020). "The SVZ areas with fewer abnormal cells, such as the SVZL and its closest tumor segment (TumorL) of Mouse 3 as well as the SVZL of Mouse 6, retained relatively higher levels of Nf1 protein expression than their autologous more advanced tumors (e.g., SVZR and TumorR of Mouse 3; Tumor of Mouse 6)." (PMID 32699356, 2020). "Cases 1, 3, and 5 were diagnosed with NF1, however, Cases 2 and 4 were not, and the tumor in Case 1 originated in the bone, whereas tumors in the other cases developed from soft tissue." (PMID 32099531, 2020). "A phase II trial with sorafenib, an inhibitor targeting BRAF, VEGFR, PDGFR and c-kit was terminated due to unexpected acceleration of tumor growth, which was not dependent on NF1 status." (PMID 31906320, 2020). "NF1 tumor growth was significantly slower than controls; however, no tumors ultimately responded to treatment." (PMID 32245042, 2020).
tumor (continued). "NF1 status did not appear as a prognostic factor, but in non-NF1 patients, a decrease in tumor volume with contrast enhancement after BB-SFOP chemotherapy was directly associated with a better visual prognosis (OR 0.8 [95% CI: 0.8–0.9], p = 0.04)." (PMID 30849081, 2019). "The authors demonstrated that by restoring miR-204 expression, cellular proliferation, migration, and invasion were decreased in NF1 and non-NF1 MPNST cell lines in vitro, and tumor growth and malignant progression were reduced in non-NF1MPNST cell lines in vivo." (PMID 31694342, 2019). "There was a negative correlation of NF1 status (affected, P = 0.037), tumor size (>10 cm, P = 0.023), and MVD in the tumor periphery (higher tercile, P = 0.002) to survival." (PMID 30735009, 2019). "The same approaches in the present study on NF2 led to the findings that, in NF2 human tumour cells, none of the pathways that were found to be affected in NF1 was affected in NF2." (PMID 31730023, 2019). "Similar to MCD, Ki‐67 LI shows a relatively similar distribution in tumor core and periphery regardless of the NF1 status." (PMID 30735009, 2019). "However, the nonsteroidal sulfamate derivatives of 2ME2 effectively promoted nuclear fragmentation in both NF1 and NF2 null tumour cell lines." (PMID 31730023, 2019). "A total of 426 tumors from 256 NF1 patients were evaluated, as well as 99 MPNST tumor samples that were sporadic or of unknown NF1 status." (PMID 31462295, 2019). "This is reflected by the state-probabilities for NF-1 patients with main tumor location in the optic pathway (n=180; 77.3%; data not shown) not to be treated at all (0.36) or to have received only one adjuvant therapy (0.45) 5 years after diagnosis." (PMID 31772664, 2019). "To test whether re-expression of NF1-LRD suppresses invasion in vivo, we transduced NF1-LRD into NF1-knockdown NNI-21 GPCs and assessed the extent of tumor invasion." (PMID 30967630, 2019). "The main possible drivers for this neoplasia were DICER1, NF1 and MYC." (PMID 29459759, 2018). "Importantly, molecular alterations in driver genes such as CTNNB1, NF1, PDGFR, PIK3CA, SH3GL1 and RBM15 were found to have a subclonal distribution, thus indicating that they have been acquired during tumor evolution." (PMID 29389895, 2018). "DeRaedt and colleagues have observed that tumor cells lacking NF1 were sensitive to reactive oxygen species-induced proteotoxic stress." (PMID 29662612, 2018). "It is currently not recommended to screen children with NF1 routinely by MRI for optic pathway gliomas, as the vast majority of tumours are indolent, and early detection does not improve visual outcomes." (PMID 29685181, 2018). "The analysis of chemoresistant patients showed that the acquired resistance to chemotherapy was associated with inactivating gene breakages at the level of the tumor suppressors RB1, NF1, RAD51B and PTEN and resistant/refractory tumors are frequently associated with CCNE1 amplifications." (PMID 29389895, 2018). "These genetic alterations involving BRAF, KRAS, RAF1, NF1, FGFR1, and FGFR2 were mutually exclusive (i.e. no tumor harbored any two of these variants simultaneously)." (PMID 29880043, 2018). "Tumor reduction was observed in all of the tumors regardless of Nf1 status (in-frame vs. premature stop indels) and the mean total percent reduction in tumor volume was 97.8% (p < 0.0001; 95% CI [94.1, 99.8])." (PMID 30182054, 2018). "The remaining five mutation positive Group 1 tumours lacking a BRAF mutation possessed an FGFR1, NF1, ARID1B, HIST1H3B, and ATM mutations, respectively." (PMID 29058119, 2018). "Given the NF1 mutation detected in the LRR and not the primary in sample A02, we re-reviewed the sequencing data on the primary tumor." (PMID 30345349, 2018).
tumor (continued). "NF1 alterations are enriched in the mesenchymal gene expression subgroup of GBM, and recent studies suggest that this gene expression subclass is influenced at least partly by the tumor microenvironment." (PMID 29643433, 2018). "On repeated neuroimaging, at the end of the follow-up period, the tumor remained stable in 8 patients in each group, progressed in 2 patients with NF-1 and 3 without NF-1, and regressed in 2 patients, both without NF-1, respectively." (PMID 30619059, 2018). "Both downregulation of EZH2 by si/shRNA or pharmacological inhibition of EZH2 in the S462 (NF1-derived MPNST) and MPNST724 (spontaneous MPNST) cell lines severely affected cellular proliferation rates, induced apoptosis and interfered with tumor formation in an MPNST724 xenograft model." (PMID 28813519, 2017). "However, by pooling these rare biopsy materials from a large number of institutions, programs like the NF1 Synodos LGG Initiative, spearheaded by the Children‘s Tumor Foundation, aim to perform comprehensive genetic and genomic sequencing of these tumors." (PMID 28066715, 2016). "Conspicuously absent are human tumor-derived cell lines or patient-derived xenograft models for NF1-LGG." (PMID 28066715, 2016). "Further work using these CSCs may reveal the critical components of the tumor microenvironment required for CSC engraftment, which might be accurately recapitulated in rodents to enable xenografting of human NF1-PA tumors in the future." (PMID 28066715, 2016). "In our study, restoration of wildtype Grb10 expression in Nf1 mutant tumor cells lacking Grb10 expression failed to suppress phosphorylation of S6Kinase upon exposure to insulin." (PMID 26000738, 2015). "In the case of the present study, immunohistochemistry for S-100 protein was negative in tumor cells, and NF1 deletion by FISH was simultaneously detected." (PMID 24932270, 2014). "Given the negative regulatory role of NF1 on RAS activation, it is conceivable that tumours which over-express miR-193b, thereby down regulating NF1, could constitutively activate the RAS signalling pathway." (PMID 23335975, 2013). "While more studies are needed to understand the contribution of MIA to NF1 pathology, the presented correlation of MIA serum level with the internal tumour load suggests that it is a promising candidate as a biomarker of the tumour load in NF1." (PMID 21726432, 2011). "There were no significantdifferences in the tumour volumes found in the NF1 and sporadic groups (P = .36)." (PMID 19360115, 2009). "For example, patients with NF1 A26465S (0.6%) at baseline experienced an 11% tumor reduction after 4 months of sotorasib treatment, and patients with SCLC with treatment-emerging NF1 N1004Ifs∗8 (0.3%) progressed with a 58% increase in tumor size, accompanied by MYC amplification (3.5-fold)." (PMID 41541668, 2026). "After a durable clinical and radiographic response, the progression biopsy demonstrated loss of MET amplification together with emergent HGF p.G401A and NF1 p.M546L, pointing to ligand reactivation and RAS/MAPK bypass as hypothesis-generating routes of escape in this tumor." (PMID 41268440, 2025). "However, other studies suggest that the difference observed is not due to NF1 itself but instead other poor prognosis factors, such as larger tumor size at the time of diagnosis, which is commonly more exaggerated in patients with NF1." (PMID 41374983, 2025). "Although fibroblasts do not represent the tumor‐initiating cell population, such as Schwann cells, they offer a genetically relevant model for evaluating cellular responses to NF1 haploinsufficiency and pharmacological interventions in a patient‐specific context." (PMID 41256734, 2025).
tumor (continued). "The enhanced response of NF1-altered tumors to radionuclide therapy may result from increased PSMA expression, greater radiosensitivity due to DNA damage response defects, or alterations in the tumor microenvironment." (PMID 41124032, 2025). "For instance, NF1 was not included in the initial NGS panels, which may have led to missed co-occurring MAPK mutations in a minority of tumours." (PMID 40107205, 2025). "When administered daily at clinically relevant exposures, the increase in pERK levels may be a transient response and therefore may not be sustained for a long duration to drive exacerbated tumor growth in preclinical NF1-LOF tumor models." (PMID 40111124, 2025). "Tovorafenib demonstrated efficacy in BRAF fusion but not in NF1-LOF mutant tumor models." (PMID 40111124, 2025). "Additionally, NF1 loss was detected in the plasma of patients with PN and MPNST but not in healthy controls, confirming the tumor origin of ccfDNA and its potential as a non-invasive biomarker of progression." (PMID 41463204, 2025). "Notably, NF1 patients exhibited higher tumor response rates, with no deaths or severe adverse events related to chemotherapy during the treatment period." (PMID 41440192, 2025). "Using an immune-competent model of de novo MPNSTs, developed through the Cas9-mediated inactivation of Nf1 and Cdkn2a, we found that the combination of CDK4/6 and MEK inhibitors uniquely induced transient tumor regression, a phenotype not seen in immune-deficient preclinical models." (PMID 40723291, 2025). "Furthermore, the association of WHO Grade 3 PXA with NF1 is exceedingly rare, and the optimal management and prognosis of this rare tumor in the setting of NF1 are not well established." (PMID 40331046, 2025). "Additionally, the binary classification approach (NF1 vs. non-NF1) does not capture the full diversity of NF1 tumor subtypes, nor does it consider patients with borderline or overlapping genetic syndromes." (PMID 40428382, 2025). "However, in both sporadic and NF1-associated MPNST, tumours can arise in the absence of an overt precursor lesion." (PMID 39409887, 2024). "Notably, PNF development in this model additionally required Nf1 heterozygosity (Nf1+/-) in non-neoplastic cells, suggesting a pivotal role of the Nf1 haploinsufficient tissue field in tumor initiation and progression." (PMID 38473354, 2024). "However, several notable tumor suppressors of modest size, including BRCA1, NF1, and RB1, could be phased completely in only around half of tumors, suggesting other locus-related features may reduce their phasing potential." (PMID 39406235, 2024). "In our studies of tumor initiation and progression, we observed that these aggressive tumors could not be transplanted into Nf1+/+ Sprague-Dawley or Athymic nude rats." (PMID 38799507, 2024). "Here authors show that inactivation of the tumor suppressors NF1, TSC1, and TGF-β RII also promotes a non-cell autonomous change in the tumor microenvironment, characterized by inflammatory features and LAG3+ T cell-mediated immune suppression, which are therapeutically targetable." (PMID 38997291, 2024). "It is conceivable that senescent Nf1-/- SCs in PNF may drive pro-inflammatory programs that promote immune cell recruitment and activation within the tumor microenvironment; however, the role of senescent SCs in PNF development and progression has yet to be definitively evaluated." (PMID 38473354, 2024).
tumor (continued). "However, tumours within Cluster 2 (NF1, RET or HRAS) had no differentially methylated probes in any comparisons between this group." (PMID 38124114, 2023). "In summary, our findings identified a novel regulatory mechanism for the oncogenic function of NF1 to regulate YAP stability through direct interaction between its PPQY motif and the WW domains of YAP1, even though NF1 was traditionally considered to be a tumor suppressor in RAS-MAPK signaling." (PMID 37147639, 2023). "In patients with NF1-associated LGG that do not respond to MEKi, FASI that overlap the LGG tumor borders may be considered." (PMID 37046770, 2023). "The GISTs without mutations in KIT, PDGFRA, SDH, or BRAF/RAS/NF1 (RAS-Pathway) were termed ‘quadruple WT’ GISTs whose diverse molecular alterations and tumor biological behaviors remain unclear." (PMID 36612101, 2022). "spOPG patients rarely had an intraorbital tumor (pathological optic nerve width in only 13/232 (6%) optic nerves; median 1.7 mm, IQR 1.55; 2.53 mm), whereas the optic nerves were commonly enlarged in NF1 + OPG patients (262/364 (72%) optic nerves; median 4.32 mm, IQR 2.97; 6.08 mm)." (PMID 34994964, 2022). "Case 1 did not have any clinical features of NF1 apart from the tumor itself." (PMID 35841038, 2022). "30% (6/20) of children with pathogenic NF1 variation and 50% (10/20) of patients without pathogenic NF1 variation, as well as 27% (8/30) of NIH positive and 30% (3/10) of NIH negative individuals had a minimum of one neoplasm." (PMID 34325699, 2021). "Altogether, NF1-deleted patients had a higher tumor burden than non-deleted NF1 patients." (PMID 34199217, 2021). "This may be due, among other reasons, to tumor heterogeneity—the mutation might not be present in all its cells—or to the loss of some tumor suppressor genes, such as PTEN and NF1, which causes primary resistance to BRAFi/MEKis." (PMID 32605090, 2020). "This poor prognosis may be contributed to 41% of patients received subtotal resection rather than wide resection, NF1 status, or large tumor size." (PMID 32998743, 2020). "Moreover, NF1 is an RAS-GTPase and an important tumor suppressor gene." (PMID 32765498, 2020). "Although the register‐based data do not allow dissecting the exact tumor types, the high incidence observed in the small intestine may largely be due to GISTs that are known to typically occur in the small intestine in NF1." (PMID 31397088, 2019). "Finally, we found that LBH589, an HDAC inhibitor, inhibited the proliferation of NF1 MPNST cells through HMGA2 and may thus be used as a targeted drug to control this tumour." (PMID 31053152, 2019). "Moreover, subcutaneous and orthotopic lung implants of Nf1‐mutant LUAD cells in nude mice exhibited decreased tumor growth when mice were administered CB‐839 or AOA, supporting glutaminase and/or Psat1 inhibition as a possible treatment strategy in Nf1‐mutant LUAD tumors." (PMID 31036704, 2019). "Interestingly, increased expression of APOBEC1 and editing of NF1 were also found in CRC, suggesting that other tumor types could also be affected by this pathway." (PMID 30619092, 2018). "The authors advised a wait-and-watch approach in such otherwise concerning cases, since current medical wisdom dictates that mass effect and enhancement of a lesion are suggestive of a tumor but at the same time tumor regression without treatment is recognized in NF1." (PMID 30410779, 2018).